ENSG00000309702 (novel transcript)
Synonyms: LOC100505912
Gene: Long non-coding RNA gene on chromosome 4 (22,327,337 to 22,339,728, reverse strand). Ensembl gene ENSG00000309702.
Diseases named in the same sentence as ENSG00000309702 in open-access papers:
ENSG00000309702 is named in the same sentence as 2 diseases in open-access papers, as found by Europe PMC text mining. Sharing a sentence is not in itself a finding about the gene and the disease.
ENSG00000309702 shares sentences with these, for which no sentence is quoted: melanoma (1 paper); tumor (1).